GATA3 (GATA binding protein 3)
Diseases named in the same sentence as GATA3 in open-access papers (continued):
Sharing a sentence is not in itself a finding about the gene and the disease.
tumor (continued). "Immunohistochemical analysis of GATA3 expression was performed, with scoring based on nuclear staining intensity and percentage of tumor cells labeled." (PMID 38161907, 2023). "We found that FRA1 was readily detected in ER− and GATA3 weak or non-detectable tumor cells, but hardly detectable in ER+ and GATA3+ tumor cells." (PMID 37353480, 2023). "GATA-3 was expressed in 78 (94%) cases, of which 67 (84%) patients had tumors where GATA-3 expression was present in >60% of tumor cells." (PMID 36996051, 2023). "We determined the tumor-initiating capacity of tumor cells and found that as low as 5 × 104 of p18mt;Gata3+/− cells were able to regenerate tumors, whereas as high as 5 × 105 of p18mt cells did not yield tumors." (PMID 37353480, 2023). "In BrCa, expression of GATA3 correlates with tumour differentiation, as it is more expressed in MCF-7 41 and controls invasiveness of MDA-MB-231 cells 42-44." (PMID 34975314, 2022). "The research results of this project suggest that the present ChIP-seq and RNA-seq analyses reveal that NRP1 is a key gene directly regulated by GATA3 and H3K4me3 that is involved in the formation of tumor cell radiation resistance." (PMID 35993027, 2022). "We and other groups identified a few tumor suppressors, p18 and caspase 14 27, 36, 40, as well as oncogenes, cyclin D and c-Myc 39, 55, as critical targets of GATA3 in controlling mammary or lymphoid cell proliferation." (PMID 34976209, 2022). "The percentage of Ck14 positive cells in Gata3 depleted tumor cells was significantly higher than in control tumor cells, confirming that depletion of Gata3 promotes basal-like differentiation in luminal tumor cells in vivo." (PMID 34976209, 2022). "GATA3, as a biological regulator of tumor cells, can form complexes with a variety of proteins to jointly regulate the transcription of target genes." (PMID 35993027, 2022). "VIRMA induces m6A methylation of the 3′ UTR of GATA3 pre-mRNA, leading to dissociation of the RNA-binding protein HuR and degradation of GATA3 pre-mRNA, promoting tumor growth and metastasis in vivo." (PMID 35784761, 2022). "All samples (except C215), which showed the increase of the TBX21/GATA3 ratio after the co-culture with tumor cells, revealed the increase of the anti-tumor reactivity." (PMID 35606862, 2022). "Mechanistically, VIRMA mediated the deposition of m6A onto the 3′-untranslated region (UTR) of Gata3, a tumor suppressor, resulting in decreased GATA3 expression and promoted resistance to apoptosis." (PMID 35350378, 2022). "For example, tumor suppressor miR-195-5p inhibits GATA3-mediated secretion of IL-4 in CRC cells and ultimately M2-like tumor-associated macrophages polarization by suppressing the NOTCH2 expression." (PMID 35574420, 2022). "The possibility of a metastatic lesion from the breast rather than a primary of the alveolus was also entertained, aided by the immunohistochemical findings of positivity of the tumor cells for GATA3." (PMID 36381227, 2022). "Thirty tumor samples were obtained, and Caveolin-1, GATA-3, and Ki67 expression was assessed by immunohistochemistry and associated with pathological factors by univariate and multivariate analyses." (PMID 36299636, 2022). "GATA3 has been reported as a critical transcription factor involved in multiple cell processes, including tumor progression and metastasis." (PMID 34980123, 2022).
tumor (continued). "In this case, with the aim of evaluating metastatic foci in mouse lungs, immunohistochemical staining of GATA3 was used as a marker of tumour cells." (PMID 36221013, 2022). "In contrast to T-bet, GATA3- and RORγt-expressing T cells, PU.1-expressing Th9 cells in tumour tissue expressed significantly more IL-9 receptor." (PMID 35793807, 2022). "The findings also showed that the mRNA expression of CNTN1, ENO1, and MAGEA1 were higher in tumor tissues, whereas the mRNA expression of GATA3 was higher in normal tissues." (PMID 35846128, 2022). "Depletion of Gata3 in luminal tumor cells also reduced cell proliferation with induction of p18 and promoted basal differentiation." (PMID 34976209, 2022). "Depletion and pharmacological inhibition of MDM2 significantly impaired tumor growth in GATA3-deficient models in vitro, in vivo and in patient-derived organoids/xenograft (PDOs/PDX) harboring GATA3 somatic mutations." (PMID 35440675, 2022). "Then, in the BLCA tumor microenvironment (TME), we comprehensively associated GATA3 with immunomodulators, cancer immune cycles, tumor-infiltrating immune cells (TIICs), immune checkpoints, and T-cell inflamed scores(TIS)." (PMID 35647011, 2022). "GATA3 was reported to upregulate the expression of miR-29b, leading to tumor microenvironment regulation and metastasis abrogation." (PMID 35804829, 2022). "Meanwhile, the over-expression of GATA3 predicts a lower tumor stage and a lower tumor grade but a higher relapse-free survival rate." (PMID 35647011, 2022). "Six SCNEC cases and two UC cases from the external cohort were immunostained for synaptophysin, CD117, and GATA3 using whole tumor sections in our institution." (PMID 35626098, 2022). "Here, we found that GATA3 was highly expressed in TC0 (tumor cells with the lowest PD-L1 expression) group and IC0 (immune cells with the lowest PD-L1 expression) group compared to other groups." (PMID 35647011, 2022). "Inversely, tumor tissues with low GATA3 expression were positively correlated with the basal subtype while indicating a high immune infiltration level." (PMID 35647011, 2022). "We also identify several segments that fall within the regulatory regions for cyclin D1, which is a known target of GATA3 in tumour cells." (PMID 35078412, 2022). "A significant number of MHC molecules were lowly expressed in high-GATA3 tissues, indicating a decline in the capacity to present and process tumor antigens in the high-GATA3 group." (PMID 35647011, 2022). "The qRT-PCR results demonstrated that expression of CNTN1, ENO1, and MAGEA1 were higher in tumor tissues, whereas the expression of GATA3 was higher in normal tissues." (PMID 35846128, 2022). "Nowadays, GATA3 has been reported to play a critical role in regulating the anti-cancer immune response in the tumor microenvironment (TME)." (PMID 35647011, 2022). "Our results show that GATA3 is required for Abl-transformed leukemic cell survival in vitro and xenografted tumor growth in vivo, revealing a critical role for GATA3 in Abl-induced tumorigenesis through regulating leukemic cell survival." (PMID 34980123, 2022). "We also found that the mPTCL expressed the Th2‐cell master regulator GATA3 and stained cells homogenously, supporting Th2‐cell biology across tumor cells." (PMID 35510955, 2022). "We generated a Gata3 positive luminal type tumor model system and discovered that depletion of Gata3 in luminal tumor cells reduces cell proliferation with induction of p18, but promotes basal-like differentiation." (PMID 34976209, 2022). "The prolonged control of mPTCL tumor progression in vivo supports the use of ATR inhibition as a single agent for the treatment of the GATA3 subgroup of PTCL." (PMID 35510955, 2022).
tumor (continued). "Tumors derived from GATA3-silenced, idasanutlin-treated cells, were very small, largely consisting of small clusters of tumor cells, compared to the larger solid tumor masses derived from GATA3-silenced cells without idasanutlin." (PMID 35440675, 2022). "By contrast, these tumours lack the typical markers for GATA3+ PTCL‐NOS such as Il2ra, il9r, and Gata3 itself." (PMID 35895495, 2022). "Tumor cells with GATA3 or GRHL2 positive nuclei also contain the pRCC marker cytokeratin 7 (CK7) in the cytoplasm, without any traces of AQP1." (PMID 35013217, 2022). "Single-cell analysis further verified that GATA3 was more highly-expressed in tumor tissues in comparison to normal tissues." (PMID 35647011, 2022). "Among these biomarkers, Caveolin-1 and GATA-binding protein 3 (GATA-3) were identified as promising markers of tumor aggressiveness." (PMID 36299636, 2022). "Together, these results indicate that depletion of Gata3 in luminal tumor cells reduces luminal differentiation but stimulates basal-like differentiation in vitro." (PMID 34976209, 2022). "Depletion of Gata3 in MMTV-PyMT luminal tumor cells further confirmed the activation of basal and impairment of luminal differentiation." (PMID 34976209, 2022). "Targeted deletion of GATA3 in tumor cells leads to apoptosis preventing the analysis of the functional loss of GATA3 in tumor cell differentiation." (PMID 34373738, 2021). "Seventeen cases (68.0%) showed at least moderate nuclear GATA3 immunoreactivity in ≥25% of tumor cells." (PMID 34829389, 2021). "Considering the most representative variants shared by tumor fragments and plasma of dogs, we identified important gene variations in ATM (C > A mutation), CCNE1 (G > C), FGFR4 (C > T), and GATA3 (G > A and C > CT)." (PMID 34680380, 2021). "TTF1 and GATA3 regularly show an inverse staining pattern and GATA3 is less expressed in more solid/spindled and sarcomatoid regions of the tumor." (PMID 33670088, 2021). "GATA3 is an established marker of luminal papillary bladder tumours which are the least aggressive tumours and still retain some of the features of the urothelial differentiation." (PMID 34690921, 2021). "In cell line models, GATA3 functions as a tumor suppressor by inducing epithelial fates while suppressing mesenchymal fates 26-28." (PMID 34373738, 2021). "Compared with adjacent normal tissues, ITGA5, CD163, STAT6 and GATA3 levels were greater in most tumor tissues." (PMID 33711961, 2021). "We were able to rule out the possibility of mixed EC and MLA because most of the tumor cells with GATA3 and PAX2 expression demonstrated moderate-to-strong nuclear immunoreactivity for ER and PR." (PMID 34829389, 2021). "When transplanted, Gata3-expressing p18-/-;Brca1MGKO tumor cells produced significantly smaller tumors with more E-cad but less Vim than Empty-expressing counterparts." (PMID 34373738, 2021). "Together, these data suggest that reconstitution of Gata3 activates MET and suppresses Brca1-deficient tumor development and metastasis." (PMID 34373738, 2021). "When the number and intensity of positive cells were quantified, we found that the H scores for Vim in p18mt;Gata3+/-tumor cells were comparable with the H scores in p18mt;Brca1+/- counterparts." (PMID 34373738, 2021). "GATA3 expression was homogeneously expressed in both cell types and tumor regions for lymph node status as well as tumor stage." (PMID 33672843, 2021). "Estrogen receptors alpha (ERα) and beta (ERβ) and the cooperating protein GATA-binding factor 3 (GATA3) have been implicated in bladder carcinogenesis and tumour progression." (PMID 34690921, 2021). "RT-qPCR examination of these tumor areas revealed a positive correlation between tumor burden and several immune genes found in ilea from pCC patients, such as Cd4, Bcl6, and Gata3." (PMID 33262469, 2021).
tumor (continued). "Since our study revealed significant associations between survival and GATA3 and CK5/6 expression, these markers were combined in a simple subgroup as luminal when the tumor had exclusive expression of GATA3 and as basal for exclusive CK5/6 expression." (PMID 34707176, 2021). "GATA3 is overexpressed in neck squamous cell carcinoma, which promotes tumor invasiveness in vitro and in vivo." (PMID 34399777, 2021). "By analysing transcription factors (TFs) with evidence of BTLA promoter binding in ChIPseq, we found each variant tumour possessed a mutation predicted to disrupt TF binding, most frequently RUNX1/3, GATA3 and MYB." (PMID 34753926, 2021). "The tumor inhibiting or tumor promoting effects of GATA3 have been widely reported in different malignant tumors." (PMID 34399777, 2021). "Knockout of Gata3 accelerates tumor onset due to the increased TIC capacity of luminal progenitor cells." (PMID 33235291, 2021). "T-bet and GATA3 are two transcription factors that determine Th cell differentiation into Th1 or Th2 cells, respectively, and both are expressed in the nuclei of tumor-infiltrating lymphoid cells." (PMID 34221962, 2021). "A series of in vitro experiments testified that USP21 regulated the expression of MAPK1 by binding to transcription factor GATA3, thereby regulating the tumor growth and cell stemness of GC." (PMID 33791299, 2021). "Several of the hub genes (GATA3, IGF1R, and FOXO3) have been reported to be associated with the tumor progression of ESCC in previous studies." (PMID 33747034, 2021). "In this process, KIAA1429 induces m6A methylation on the 3'UTR of the GATA3 pre-mRNA, leading to the separation of the RNA-binding protein HuR and the degradation of the GATA3 pre-mRNA, inducing tumor growth and metastasis." (PMID 34422053, 2021). "The tumor cells were strongly immunoreactive for GATA3 with focal weak expression of pan cytokeratin." (PMID 34449584, 2021). "Functionally, GATA3 expression in BC cell lines and murine models reduces the tumor-initiating ability, the epithelial to mesenchymal transition, and the metastatic potential." (PMID 33800667, 2021). "For certain genes (Il10, Csf3, Cxcl1, Ccl2, Gata3, Il5, and Il13), there was a clear difference between the EC and HC Shb KO effects using Cdh5-CreERt2 or Vav1-Cre tumor-bearing mice, indicating that these effects reflect EC cell autonomy of Shb gene deletion." (PMID 34768912, 2021). "In MF, GATA3 expression is increased and high expression of GATA3 was retained in MyLa cells after co-culture with MF tumor-derived fibroblasts." (PMID 33941102, 2021). "As GATA3 protein has a role in expression regulation, lower level of SMR3B expression in tumor carrying GATA3 mutations can be explained by this fact." (PMID 33462316, 2021). "Morphology analysis revealed that some of the Gata3-expressing p18-/-;Brca1MGKO tumor cells were cuboidal shaped epithelial-like cells whereas all Empty-expressing cells were spindle-shaped, mesenchymal-like cells." (PMID 34373738, 2021). "In particular, highest expression levels of GATA3 have been observed in the luminal A subtype of ER-positive tumours." (PMID 33298139, 2020). "Both mRNA (P < 0.001) and protein levels of GATA3 were significantly downregulated in tumor tissue samples." (PMID 31636361, 2020). "We have identified that CTSV promotes ER-positive breast cancer through facilitating tumour cell proliferation, invasion and suppressing the expression of GATA3." (PMID 33298139, 2020). "The luciferase activity of the GATA3-shRNA group was enhanced and the area of tumor spread was large." (PMID 32760217, 2020). "Gene silencing of GATA3 was documented in several cancers and re-expression of GATA3 was capable of inhibiting tumor metastasis." (PMID 33324547, 2020).
tumor (continued). "On the other hand, in PC pro-tumor Th2 CD4+ (GATA3+) sub-populations are more represented than the tumor-killing Th1 (T-bet+) and their levels correlate with poor prognosis." (PMID 32012917, 2020). "A similar positive correlation between MAGI1, ESR1, and GATA3 expression is also found in tumor samples derived from the MMTV-PyMT spontaneous model of BC." (PMID 31963297, 2020). "The overexpression of KIAA1429 induces tumor growth and metastasis by inducing the separation of the HuR binding and degradation of GATA3 pre-mRNA." (PMID 33519919, 2020). "miR-455-3p mediates GATA3 tumor suppression in mammary epithelial cells by inhibiting TGF-ß signaling." (PMID 32805720, 2020). "Somatic mutations in these genes were often heterogeneously present throughout the different tumour components, and their presence seemed unrelated to the HER2 amplification status, except for GATA3 mutations." (PMID 32058674, 2020). "To investigate the GATA3 expression in ccRCC, we collected 30 pairs of tumor tissue samples and adjacent normal tissue samples from ccRCC patients." (PMID 31636361, 2020). "DOX and T. pratense extract synergistically down‐regulated MMP‐2 and up‐regulated SIRT‐1 genes, decreased the number of CK5/6‐positive cells in tumor tissues, and inhibited metastasis of GATA‐3‐positive cells into the lung and brain." (PMID 33133558, 2020). "GATA3 is considered to be a tumor suppressor in CRC and involve in miRNAs-mRNA co-regulatory networks of CRC." (PMID 32760217, 2020). "The percentage of GATA3 staining tended to be higher than that of CK20, and CK20 staining was stained on GATA3-positive tumor cells in most cases." (PMID 31469885, 2019). "If we use the 80% cut-off to define the basal/squamous-like phenotype (CK5/6 and GATA3 staining in >80% and ≤80% of tumor cells, respectively), this subgroup would account for 20 (22.0%) cases in our MIBC cohort." (PMID 31469885, 2019). "As in previous studies, the frequency of either p63- or GATA3-positive tumor cells in each case is variable but generally very low." (PMID 31831043, 2019). "We suggest that the presence of alveolar fibrosis and p63 expression strongly indicates PMLBCL, whereas GATA3 positivity favors CHL even when GATA3 is expressed in a very low proportion of tumor cells." (PMID 31831043, 2019). "As a cell-differentiation regulator, GATA3 is a strong and independent predictor of tumor grade, estrogen-receptor (ER) status, and clinical outcome in human breast cancer." (PMID 31685800, 2019). "In those tumours for which survival data were available, relapse-free survival and overall survival were both worse in patients whose tumours expressed more GATA3 protein than FA." (PMID 31831790, 2019). "Our findings provide a new perspective on the tumor suppressor activity of GATA3 in mammary epithelial cells." (PMID 31754326, 2019). "GATA3 improves the anti-cancer ability of T lymphocytes in the tumor microenvironment by the ENTPD3-catalyzed hydrolysis of eATP." (PMID 31754326, 2019). "This is the practical reason why p63 is preferable to GATA3 because of a relatively higher proportion of positive tumor cells." (PMID 31831043, 2019). "In the present study, we verify that ENTPD3 is a novel downstream target of GATA3 and is essential for its role as a tumor suppressor." (PMID 31754326, 2019). "In vivo, re-expression of LH2 in GATA3-depleted cells facilitates their xenograft tumor growth and metastatic capacity." (PMID 30093726, 2018).